BCL2 (BCL2 apoptosis regulator)
Diseases named in the same sentence as BCL2 in open-access papers (continued):
Sharing a sentence is not in itself a finding about the gene and the disease.
breast carcinoma (continued). "Although combined inhibition of Bcl-2 and Bcl-xL using ABT-263 is capable of inducing apoptosis in ERɑ+ breast cancer cells, rapid Mcl-1 upregulation in response to ABT-263 limits the extent to which apoptosis is induced in these cells." (PMID 31595181, 2019). "As expected, many established oncogenes in distinct malignancies were detected including ERBB2 in breast cancer, MET in stomach tumor and BCL2 in leukemia/lymphoma." (PMID 31050342, 2019). "In breast cancer cell lines, fucoidan (F. vesiculosus) induced apoptosis, as well as reducing the protein levels of ERK1/2, survivin and Bcl-2 in vitro." (PMID 30621045, 2019). "The CHIP-silencing inhibited the AGS cell apoptosis due to increased expression of Bcl-2, which is in line the previous report that CHIP-knockdown can regulate the Bcl-2 expression level in breast cancer." (PMID 31130821, 2019). "In conclusion, we identified a novel Bcl-2 inhibitor by QSAR screening, which exerted significant cytotoxic activity in breast cancer cells through inducing mitochondria-mediated apoptosis." (PMID 31057406, 2019). "Further, we report that the combined inhibition of Mcl-1 using VU661013 with blockade of Bcl-2/Bcl-xL using ABT-263 resulted in superior tumor cell killing and tumor growth inhibition in ERα+ breast cancers in culture and in vivo." (PMID 31595181, 2019). "As in other types of breast cancer, TGF-β-mediated regulation of N-CADHERIN, BCL2, and CYCLIN D1 determines EMT and stemness in MDA-MB-231 TNBC cells." (PMID 31075939, 2019). "Treating breast cancer cells with a combination of WFA and sulforaphane (SFN) induces apoptosis via upregulation Bax/Bcl-2 ratio and downregulation of HDAC1 expression." (PMID 31618928, 2019). "Here, from the analysis of the TCGA-BRCA dataset, we uncovered the gene expression landscape of globular Bcl-2 members and their putative BH3-like interactors in breast cancer." (PMID 31825969, 2019). "Silencing antiapoptotic genes such as BCL-2 and BCL-xL via the application of siRNAs delivered by hybrid nanoparticles was shown to be an effective and promising strategy against breast cancer." (PMID 31064156, 2019). "We find, in a model of MYC-driven breast cancer, that pharmacological activation of AMPK strongly synergizes with BCL-2/BCL-XL inhibitors to activate apoptosis." (PMID 30728358, 2019). "We analyzed the changes in the expression of the Bcl-2 proteins and their BH3-containing interactors in breast cancer samples." (PMID 31825969, 2019). "The mammary tumors from DMBA control group showed extensive Bcl2 protein expression, and YHHY treatment exhibited considerable inhibition of Bcl2 expression." (PMID 30760265, 2019). "In this study, the authors demonstrate that AMPK activation and BCL-2/BCL-XL inhibition have a synergistic effect on apoptosis, and that together with anti PD-1 therapy they can suppress Myc-driven mammary tumor growth." (PMID 30728358, 2019). "First, we performed MTT assays in a 6×6 dose matrix format to test for any synergistic activity between BCL2 inhibitors and 2DG in either ER+ MCF7-pSFFV or TNBC HDQ-P1 breast cancer cells." (PMID 29899841, 2018). "In another study, curcumin generated a miR-15- and miR-16-mediated downregulation of Bcl-2-induced apoptosis in MCF-7, Bcap-37, and SKBR-3 breast cancer cell lines." (PMID 30092754, 2018). "As a result, an increased ceramide level can activate apoptosis by enhancing the expression of the pro-apoptotic protein Bcl2 which interacts with protein 3 (BNIP3), as reported in breast cancer cells." (PMID 29588626, 2018). "Lemon citrus extract have also shown to upregulate bax, and caspase-3 genes expression, downregulate bcl-2 gene expression, and consequently, induce apoptotic cell death in MCF-7 Breast cancer cells." (PMID 30224635, 2018).
breast carcinoma (continued). "Enrichment analysis and experimental validation demonstrated that ADQ might improve breast cancer chemosensitivity via inhibiting caveolin-1, which further triggered expression changes of cell cycle-related proteins p21/cyclinB1 and apoptosis-associated proteins PARP1, BAX and Bcl-2." (PMID 30333750, 2018). "Further, E2 is able to induce BCL-2 and CCND1 in breast cancer cells and they are downstream from AKT1." (PMID 29416771, 2018). "IGF1R, BCL2, and MET, which promotes breast cancer progression and tumor metastasis, composed interaction models with various miRNAs." (PMID 28793339, 2017). "The results suggest that signaling proteins affected by EGCG in breast cancer, which include JUN, FADD, NFKB1, Bcl-2, GNAO1, and MMP14, are involved primarily in cell death and survival; DNA replication, recombination and repair; and the cell cycle." (PMID 28713815, 2017). "In particular, we identified JUN, FADD, NFKB1, Bcl-2, GNAO1, and MMP14 as potential targets of EGCG in breast cancer." (PMID 28713815, 2017). "Similar results were given when EG was tested against the human breast cancer cells (MDA-MB-231 (ER-) invasion and showed to modulate the PI3K/Akt pathway and to inhibit their downstream targets such as Bcl-2/Bax at mRNA levels." (PMID 28441723, 2017). "Treatment of human breast cancer (MCF-7) cells with Cladosporol A decreased ΔΨm, upregulated Bax expression and downregulated Bcl-2 levels in a concentration-dependent manner, thereby increasing the ratio of Bax/Bcl-2 protein levels." (PMID 28728544, 2017). "The Cancer Genome Atlas (TCGA) Network analyzed breast cancers using RPPA and defined a luminal tumor subtype that showed high ER, AR, and BCL2 protein expression." (PMID 29050296, 2017). "Artichoke polyphenols modify Bcl-2 and BAX expression in human breast cancer cell line MDA-MB-231, leading to a pro-apoptotic situation, which was accompanied with the upregulation of p21." (PMID 29112149, 2017). "A study explored the role of BCL-2 as a potential therapeutic target in breast cancer and showed a sensitization of BCL-2 expressing breast cancers to chemotherapy by the BH3 mimetic ABT-737." (PMID 29099748, 2017). "In another study, aptamer AS1411 targeting a Bcl-2 mRNA-binding protein nucleolin was examined for the ability to induce Bcl-2 mRNA instability and cytotoxicity in MCF-7 and MDA-MB-231 breast cancer cells." (PMID 29132385, 2017). "miR-205 is involved in EMT and acts through the anti-apoptotic protein Bcl-2 (in prostate cancer) and HER3 (in breast cancer)." (PMID 28239461, 2017). "Specifically, BCL2 was highly expressed in 7/14 (50.0%) of HPV-positive and 14/67 (20.9%) of HPV-negative breast cancers." (PMID 29423411, 2017). "UCA1 binding to miR-143 was proved in breast cancer, where UCA1 was able to modulate cell growth and apoptosis by downregulating miR-143: this in turn led to upregulation of BCL2 (BCL2, apoptosis regulator) and ERBB3 (erb-b2 receptor tyrosine kinase 3)." (PMID 29147648, 2017). "Inhibition of STAT3 by both curcumin and its analogue hydrazinocurcumin blocks protein expression of both Mcl-1 and Bcl-2 in MDA-MB-231 and MCF-7 breast cancer cells." (PMID 29262529, 2017). "In contrast to the observation that Bcl-2/Bcl-xL were primarily expressed in ER-positive breast cancer cells, we found that MDA-MB-231 TNBC cells exhibited much higher level of Bcl-2 and Bcl-xL compared to ER-positive MCF-7 breast cancer cells." (PMID 28415735, 2017).
breast carcinoma (continued). "Several nodes in this pathway emerged as potential direct targets of EGCG in breast cancer: JUN, FADD, NFKB1, Bcl-2, GNAO1, and MMP14." (PMID 28713815, 2017). "We assessed the pro-apoptotic gene BAX and the anti-apoptotic gene BCL-2 with combinatorial WA and SFN as well as singly administered SAHA and found there to be an inverse relationship in these treated breast cancer cells." (PMID 28534825, 2017). "ARTN activation of AKT was previously demonstrated to promote the expression of BCL-2 and TWIST1 resulting in enhanced oncogenicity and an increased CSC population in breast cancer." (PMID 26675549, 2016). "EGCG interacts with target proteins in the breast cancer cells, such as ERα, Zap-70, PI3K, G3BP1, IGF-1R, vimentin, Bcl-2, Bcl-xL, GRP78, and Fyn via hydrogen bonding, which plays a role in the inhibition of breast cancer." (PMID 27483305, 2016). "In this study, a decreased level of Bcl-2 and increased level of BAX were observed in breast cancer cells after ZLD1039 treatment." (PMID 26868841, 2016). "Dioscin-induced breast cancer cell death via AIF-facilitated caspase-independent pathway and the down regulation of anti-apoptotic proteins as Bcl-2, cIAP-1, and Mcl-1." (PMID 27751178, 2016). "Study found there was an increase of Bcl-2/Bax ratio in PTX-resistant breast cancer cell lines, high ratio reduced the PTX-induced apoptosis in breast cancer and ovarian cancer cells." (PMID 26900348, 2016). "We investigated the levels of MCL-1 and the other BCL-2 family members BCL-2, MCL-1, BIM, PUMA and NOXA in 32 human breast cancer and immortalized breast epithelial cell lines." (PMID 27931239, 2016). "Overall, miR-21 functions as an oncomiR and modulates tumorigenesis through regulation of genes such as ANKRD46, BCL2, TIMP3, PDCD4, PTEN, TPM1, and MASPIN in breast cancer." (PMID 27746811, 2016). "Ursolic acid has previously been demonstrated to induce apoptosis by causing the release of cytosolic cytochrome c, activating caspase-3, reducing the expression of Bcl-2 and increasing the expression of Bax in HeLa and MDA-MB-231 breast cancer cells." (PMID 25621065, 2015). "Specifically, miR-34a directly down-regulates the expression of BCL-2 and SIRT1, inhibiting the proliferation and migration of breast cancer cells." (PMID 26423775, 2015). "In breast cancer cells, it is reported that VEGF acts as survival factor and prevents apoptosis by inducing Bcl-2 expression." (PMID 26551008, 2015). "Specifically in the context of breast cancer, Mcl-1 has genetic or mRNA upregulation in 16/58 (28%) of human breast cancer cell lines as curated by the CCLE, while Bcl-2 is only aberrantly upregulated in 2/58 cases (3%)." (PMID 25784482, 2015). "Our data is in contrast to previous siRNA experiments, where silencing of GLI1 resulted in increased apoptosis and reduced level of anti-apoptotic Bcl-2 in HCC, glioma and breast cancer cells." (PMID 25544756, 2015). "Curcumin increased the percentage of breast cancer cells with low level of HER2 in the subG1 population and these data were confirmed by increased Bax/Bcl-2 ratio." (PMID 26694341, 2015). "Meanwhile, down-regulation of Akt1 resulted in the suppression of Bcl-2, P-gp and COX-2, and increase of Bax expression in breast cancer cells." (PMID 26359357, 2015). "In contrast, there was significant up-regulation in Bcl-2 and HER-2 mRNA expression levels in breast cancer cells with ER−, PR− and HER-2− status." (PMID 25292288, 2014).
breast carcinoma (continued). "A large number of genes were predicted as targets of the selected miRNAs, including many well-known genes that are deregulated in breast cancer, such as CCND1, BCL2, E2F3 and PTEN." (PMID 24788655, 2014). "Oncogenes Bcl2, c-myc and Vascular Endothelial Growth Factor (VEGF) are also reported to be a breast cancer-specific estrogen-responsive genes." (PMID 25070479, 2014). "Following silencing of the β2-M by siRNA, the levels of Bcl-2, ER, PR and HER-2 transcripts and the protein expression levels in human breast cancer cells were measured by real-time PCR and western blotting, respectively." (PMID 25292288, 2014). "Bcl-2 is a target protein of the ER genome singling pathway in breast cancer cells (MCF-7), and modulates apoptosis in breast cancer cells." (PMID 25292288, 2014). "ABT-737 is an inhibitor of BCL-XL (BCL2L1), BCL-w (BCL2L2), and BCL-2 that has been shown to enhance cell death, including in MCF7 breast cancer cells and myeloma cells by binding and inhibiting the activity of antiapoptotic BCL2 family members." (PMID 24745479, 2014). "This aptamer was tethered to Bcl2 siRNAs and evaluated as a potential therapeutic approach for sensitizing HER2-positive mammary carcinoma cells to chemotherapy." (PMID 23894227, 2013). "Bcl-xL has been shown to be involved in breast cancer metastasation and CRC migration, but the role of Bcl-2 and Mcl-1 to tumor spread remains unsolved." (PMID 24098503, 2013). "Our data demonstrated that embelin is able to change the mitochondrial membrane potential to promote a change in the levels of Bax and Bcl-2 as well as the release of cytochrome C, which results in the apoptosis of MCF-7 breast cancer cells." (PMID 23425971, 2013). "It was also reported that WT1 is required for inhibition of apoptosis in breast cancer and rhabdoid cancer by decreasing Bcl-2 mRNA and protein levels; however, other reports indicated that WT1 negatively regulated the Bcl-2 promoter in the prostate cell line." (PMID 23936312, 2013). "We developed a prognostic tool for early breast cancer based on the analysis of the relative expression level of FGF18, BCL2, PRC1, MMP9 and SERF1A in combination." (PMID 23648477, 2013). "In breast cancer cell lines, hypoxia-stimulated VEGF expression was increased by overexpression of Bcl-2." (PMID 22949815, 2012). "In breast cancer cells, ectopic expression of Raf could increase the protein levels of Bcl-2, which is likely to be due to the enhanced phosphorylation of downstream transcription factors that bind to the promoter region of Bcl-2 upon activation of the pathway." (PMID 23316476, 2012). "miR-195 was shown to inhibit cyclin D1 in HCC and breast cancer, CCND3 in glioblastoma, CDK4 in bladder cancer, CDK6 in HCC, E2F3 in HCC and glioblastoma, BCL-2 in breast and colorectal cancer, RAF1 in breast cancer, and GLUT3 in bladder cancer." (PMID 23335942, 2012). "Akt plays a known pro-survival function in breast cancer cells, where it relays signals from upstream molecules including integrins, growth factor receptors, PI3K and mTORC1 to downstream molecules such as Bcl-2 and NF-κB." (PMID 22776333, 2012). "The predominant form, PL2L60, is mainly expressed in tumor cells and promotes cell survival and proliferation of a human breast cancer cell line (MDA-MB-231), possibly by the upregulation of Bcl2 and Stat3." (PMID 22748119, 2012). "The stability of anti-apoptotic proteins Mcl-1 and Bcl-2 was also assessed in these MDA-MB-468, MDA-MB-231 and MCF-7 breast cancer cells after treatment with CHX (200 μg ml–1)." (PMID 21730980, 2011).
breast carcinoma (continued). "The expression of BCL-2 and BAD gene in breast carcinoma tissues were indicated by brown granules, mainly distributes in the cytoplasma, and non-uniform; The positive expression of BCL-2 and BAD in breast carcinoma." (PMID 20691103, 2010). "In this study we find that the expression of BCL-2, BAD in tissues of breast carcinoma are significantly lower than tissues of normal breast and tissues of breast fibroma." (PMID 20691103, 2010). "In this study we found that the expression rates of BCL-2 and BAD in tissues of youth breast carcinoma were significantly lower than in the tissues of menopause breast carcinoma." (PMID 20691103, 2010). "Immunohistochemical technique was used to detect the expression of BCL-2, BAD in 10 normal breast tissues, 10 breast fibroadenoma tissues, 40 youth human breast carcinoma tissues, 40 menopause human breast carcinoma tissues." (PMID 20691103, 2010). "Detecting the expression of the BCL-2 protein expression level, in particular the combined detection of the expression of BCL-2 and BAD as well as ER and PR were helpful in the prognosis of breast carcinoma." (PMID 20691103, 2010). "Sensitisation to the pro-apoptotic effects DIAs is mediated by decreased expression of BCL2, which we show here is a direct MYB target in breast cancer cells." (PMID 20659323, 2010). "Previously, FOXO3a has also been shown to induce the expression of the cell cycle inhibitor p27Kip1 and the pro-apoptotic Bcl-2 protein Bim to induce proliferation arrest and apoptosis, respectively, in MCF-7 breast cancer cells." (PMID 20808831, 2010). "The expression of BCL-2, BAD genes in young human breast carcinoma tissues were lower than that in menopause human breast carcinoma tissues (P < 0.05)." (PMID 20691103, 2010). "We report the roles of BCL2L2 (BCL-W), BCL2, and Beclin-1 (BECN1) in affecting responsiveness to ICI-resistance, and describe how anti-apoptotic BCL2 family members are involved in determining breast cancer cell fate." (PMID 20062536, 2010). "For this reason we assessed the effect of WT1–ZF on the expression of WT1 itself, and on the expression of Bcl-2 and c-myc in the context of WT1-expressing breast cancer cell lines." (PMID 17634147, 2007). "In keeping with this observation, we also showed that the expressions of two other WT1 targets, Bcl-2 and c-myc, are repressed by WT1–ZF in breast cancer cell lines." (PMID 17634147, 2007). "Ruiz-Ruiz and Lopez-Rivas have suggested that, in breast cancer cell lines, IFNγ favors activation of mitochondria-operated apoptotic pathway by TRAIL; this activation can be inhibited in bcl-2 overexpressing cells." (PMID 17697357, 2007). "Tissue samples from 44 patients with breast cancer were used to assess telomerase activity using the TRAP method and the expression of ERα, ERβ and bcl-2 by means of immunocytochemical techniques." (PMID 16911782, 2006). "E2 has been shown to increase the production of bcl-2 in MCF-7, an ER-α positive cell line of breast cancer." (PMID 15777479, 2005). "An aim of the present study was to clarify the involvement of bcl-2 and cytochrome c release in ZOL mediated caspase activation in breast cancer cells." (PMID 11986784, 2002). "One of the aims of the present study was to clarify the involvement of bcl-2 and cytochrome c in caspase activation induced by the N-BP, ZOL in breast cancer cells." (PMID 11986784, 2002).